IL6 (interleukin 6)
Diseases named in the same sentence as IL6 in open-access papers (continued):
Sharing a sentence is not in itself a finding about the gene and the disease.
Obesity (continued). "Recently, it is reported that the inflammatory cytokines of TNF-α and IL-6 are elevated in sleep apnea and obesity and might play a role in the pathogenesis and pathological sequelae of both disorders." (PMID 24466027, 2014). "Unlike many inflammatory cytokines (such as IL-1 and IL-6) that have been identified as causing cachectic effects, the effect of G-CSF results not from cachectic effects, but from anti-obesity effects." (PMID 25144367, 2014). "Thus, further studies are needed to evaluate the role of IL-6 and IL-18 in the pathogenesis of obesity and insulin resistance." (PMID 24733068, 2014). "Obesity is a low-grade systemic inflammatory condition mediated by cytokines such as TNFα and IL-6." (PMID 25144367, 2014). "The accumulation of adipose tissue macrophages (ATMs) is a hallmark of obesity-induced adipose inflammation, and inflammatory mediators (TNF-α, IL-6, and MCP-1) released from the ATMs play a crucial role in promoting obesity-related systemic inflammatory conditions." (PMID 25477711, 2014). "Taken together, the data suggest that obesity-related reductions in neutrophil recruitment induced by subacute O3 exposure are the result of reduced IL-17A-dependent G-CSF release, consequent to reduced IL-6 and IL-23 expression." (PMID 24823369, 2014). "Plasma IL-6 was also significantly elevated by obesity in parous mice." (PMID 25354395, 2014). "Moreover, a recent study identified progranulin as a key adipokine that triggers systemic insulin resistance, adipocyte hypertrophy, and obesity through production of IL-6 in adipose tissue." (PMID 24098801, 2013). "Diet-induced obesity-associated inflammation is characterized by an increased abundance of M1 macrophages in the adipose tissue, which are postulated to be major sources of several molecular mediators, such as TNF, IL-6, and C-reactive protein." (PMID 23922979, 2013). "Resistin and the proinflammatory cytokines, such as TNF-α, IL-6, and IL-1β, produced by adipocytes, and macrophages, are considered to be important modulators of chronic inflammation contributing to the development of obesity and atherosclerosis." (PMID 23484124, 2013). "However, we did find associations between the less researched SNPs IL-6 IVS4 +869 A > G (rs2069845) and IVS3 +281 G > T (rs1554606) and obesity and serum lipid profiles in black and white SA women." (PMID 23698162, 2013). "In addition adoptive transfer experiments of cytokine-deficient mast cells showed a key role of IL6 and INF-γ produced by mast cells in developing diet-induced obesity and glucose intolerance." (PMID 24084730, 2013). "The role of IL-6 in obesity and insulin resistance is controversial." (PMID 23781214, 2013). "The macrophage accumulation in adipose tissue under an inflammatory state is a hallmark of obesity-induced insulin resistance, and the macrophages are responsible for almost all adipose tissue expression of TNF-α and IL-6, the markers of adipose macrophage polarization and inflammation." (PMID 23533500, 2013). "Moreover, the levels of macrophage M1 phenotype, MCP-1, TNF-α, IL-6, and IL-1β are elevated in obesity and insulin resistance, and these factors play a major pathophysiological role in heart failure." (PMID 24454978, 2013). "This drug not only reduced the inflammatory responses in adipocytes (e.g., it caused a downregulation of inflammatory markers such as tumor necrosis factor-α and interleukin-6) but also in vivo Bay-X-1005 prevented hepatic steatosis created in a mouse model of dietary obesity." (PMID 23762565, 2013). "Several other growth factors and cytokines upregulated in obesity, such as IL-6, IL-8, IGF-1, and TGFβ, may also influence prostate cancer cell proliferation." (PMID 23573093, 2013). "It is therefore not surprising that higher circulating concentrations of IL-6 have been associated with obesity, especially visceral fat deposition, and decrease in response to weight loss." (PMID 23698162, 2013).
Obesity (continued). "Obesity is recognized as being associated with a chronic, low-grade, inflammation, with altered levels of several circulating factors such as C-reactive protein (CRP), tumor necrosis factor α (TNF-α), and interleukin-6 (IL-6)." (PMID 23409006, 2013). "IL-6 by itself further increases the production of CRP in obesity." (PMID 23617205, 2013). "Thus the role IL-6 in obesity and insulin resistance likely depends upon the specific sites of expression that is integrated with other adipokine/cytokine factors in a systems integrated manner." (PMID 23781214, 2013). "IL-6−/− mice also develop hepatosteatosis, systemic IR, and mature-onset obesity." (PMID 23921145, 2013). "The circulating levels of IL-6 are higher in subjects with obesity-related insulin resistance." (PMID 24106481, 2013). "Further research with attention to obese patients might ascertain presumable correlations of IL-6 and CRP with adipokines as well as adiponectin, which are commonly related to obesity-associated pathologies." (PMID 24023413, 2013). "IL-6 knock-out mice develop late onset obesity and impaired glucose tolerance." (PMID 23861558, 2013). "In addition to exerting both pro- and anti-inflammatory functions, IL-6 also plays important roles in both obesity and physical exercise." (PMID 23576853, 2013). "In addition, they also noted an increasing trend with other pro-inflammatory markers like TNF-α and IL-6 with overweight/obesity." (PMID 24025484, 2013). "IL-6 is highly expressed in adipose tissue and positively correlated with obesity in humans." (PMID 23781214, 2013). "Ablation of IL-6 or TNFR1 blocked obesity-promoted hepatocarcinogenesis." (PMID 23819063, 2013). "Obesity is characterized by an excessive increase in the amount of adipose tissue, which acts as an organ secreting a large variety of proteins, including the proinflammatory cytokines interleukin-6 (IL-6) and TNF-α." (PMID 23533315, 2013). "Furthermore, ‘triple-negative’ breast cancers have been found to correlate with inflammatory states such as obesity and diabetes where pro-inflammatory cytokines, including IL-6, are highly expressed." (PMID 23372803, 2013). "This suggests that obesity-induced IL-6 secretion may reflect a mechanism to increase insulin production in the obese IR state." (PMID 23675368, 2013). "These obesity-attributable illnesses have been discovered to have a strong association with inflammatory parameters in plasma such as proinflammatory cytokines (TNF-α and IL-6)." (PMID 24324381, 2013). "The relationship between insulin sensitivity and circulating zonulin might be mediated through the obesity-related circulating IL-6 increase." (PMID 22629362, 2012). "It remains to be seen how changes in glucose tolerance and insulin sensitivity, as impaired by obesity or ameliorated by exercise, might be reflected in the pattern of IL-6 response." (PMID 22347395, 2012). "Adipose tissue insulin resistance may occur in obesity in part through the infiltration of macrophages which release pro inflammatory cytokines such as TNFα, IL-6 and IL1β." (PMID 22363403, 2012). "Similarly, in prostate cancer, serum levels of IL-6 were higher in patients with obesity/insulin resistance and clinically evident hormone-resistant prostate cancer, compared to those with hormone-dependent cancer." (PMID 22701472, 2012). "However, this view has been recently challenged since serum IL-6 elevation was commonly observed in patients with metabolic disorders such as obesity and/or diabetes." (PMID 22623023, 2012). "In conclusion, the relationship between insulin sensitivity and circulating zonulin might be mediated through the obesity-related circulating IL-6 increase." (PMID 22629362, 2012).
Obesity (continued). "Linear and logistic regression and dose-response curves were used to evaluate relations of tCys with obesity, insulin resistance and inflammatory markers including interleukin-6 (IL-6), tumor necrosis factor-alpha (TNF-α), monocyte chemoattractant protein-1 (MCP-1) and C-reactive protein (CRP)." (PMID 22984471, 2012). "Moreover, the IL6 global knockout mouse model is insulin-resistant, whilst the IL6 transgenic mouse is protected from diet-induced obesity and insulin-resistance." (PMID 22474579, 2012). "Aside from this, obesity can perpetuate both systemic and pulmonary inflammation, since excessive adipose tissue is able to produce various proinflammatory cytokines including interleukin-6 (IL-6) and tumor necrosis factor alpha (TNF-α)." (PMID 23101436, 2012). "However, it is important to note that BMI also affects WBC count, with obesity creating a proinflammatory state characterized by increases in C reactive protein and interleukin 6 concentrations as well as in WBC count." (PMID 22613769, 2012). "Indeed, IL-6 knockout mice develop moderate obesity, glucose intolerance and dyslipidemia at 9 months of age." (PMID 22761857, 2012). "Our data indicate that negative control of IL-6 signaling is increased in myocytes in obesity, whereas a dysfunctional IL-6 signaling is established further downstream of IL-6Rα in DM myocytes, resulting in a failure in activating gene expression and metabolic rate." (PMID 22761857, 2012). "Considering that central obesity and resulting adipocyte hypoxia increase systemic IL-6, it stands to reason that adipocyte hypoxia may be involved in the hypoferremia of obesity through increased inflammatory signaling of hepcidin." (PMID 21912548, 2011). "Interestingly, like in the case of obesity and insulin resistance, the effect of CRP and IL-6 on the amylin-MetS association was rather minor." (PMID 21935471, 2011). "Extending these observations to other settings of muscle wasting and elevated IL-6 and related cytokines, STAT3 activation might also mediate muscle loss in obesity, advanced age or sarcopenia, inflammatory myopathies, burn, and other diseases." (PMID 21799891, 2011). "Although the CTC levels determined in this study do not allow us to clearly conclude that the inflammatory cytokine-HPA axis feedback is dysregulated in obesity, the results do suggest reduced responsiveness to high levels of IL-6 in corticosterone release in the obese Zucker rats." (PMID 21599899, 2011). "IL-6 is considered the major inflammatory mediator in obesity." (PMID 21352586, 2011). "IL-6, a proinflammatory cytokine, is also involved in obesity-related insulin resistance." (PMID 21960997, 2011). "Interleukin-6 (IL-6) is considered the major inflammatory mediator in obesity." (PMID 21352586, 2011). "Obesity is associated with "low-grade inflammation", a term that is used to reflect increments in the systemic concentration of tumour necrosis factor-alpha (TNF-α), interleukin (IL)-1β, IL-6, IL-1ra, and C-reactive protein (CRP)." (PMID 21599899, 2011). "Furthermore, TNFα decreases adiponectin expression and stimulates the secretion of proinflammatory proteins (for example, IL-6), which contribute to the maintenance of the chronic inflammatory state of adipose tissue in obesity." (PMID 21410966, 2011). "Research suggested that obesity could facilitate asthma through a persistent, low-grade inflammation mediated by multiple cytokines, chemokines, and acute-phase proteins, such as interleukin-6." (PMID 21740558, 2011). "Genetic deletion of IL-6 attenuates angiotensin II-induced hypertension in mice, suggesting that elevated IL-6 in obesity might contribute to hypertension via Ang II." (PMID 21410966, 2011). "Increased circulating concentrations of IL-6, which may occur in response to inflammatory condition such as sepsis, inflammatory bowel disease, and obesity, stimulate hepcidin transcription through a STAT3-dependent mechanism." (PMID 21912548, 2011).
Obesity (continued). "Indeed, biomarkers of inflammation such as leucocyte count, tumor necrosis factor α (TNFα), interleukin-6 (IL-6) and C-reactive protein are increased in obesity and predict the development of T2D." (PMID 21826222, 2011). "Obesity stimulates CRP synthesis mainly due to circulating levels of IL-6." (PMID 20646281, 2010). "IL-6 is thought to play an important role in the inflammatory-related pathogenesis of obesity." (PMID 20877574, 2010). "Furthermore, targeted ablation of the IL-6 gene in one mouse model resulted in mature onset obesity and insulin resistance while a second, independent study on IL-6−/− mice, did not exhibit differences in body weight compared to wild type animals." (PMID 21179199, 2010). "Moreover, further studies confirmed that ATMs recruited to AT in diet-induced obesity express high levels of IL-6, inducible nitric oxide (NO) synthase (iNOS) and CCR2, all characteristics of the M1 phenotype." (PMID 20508742, 2010). "This is supported by clinical and epidemiological studies showing larger venular caliber to be associated with systemic biomarkers of inflammation, including C-reactive protein and interleukin-6, and with impaired fasting glucose metabolism, dyslipidemia, obesity and cigarette smoking." (PMID 21060863, 2010). "The adipokines with black lettering are those whose circulating levels are enhanced in obesity and whose total release by adipose tissue explants is enhanced in obesity: IL-6, IL-10, ACE, TGFβ1, ICAM-1, TNFα, IL-1β, PAI-1, and IL-8 that are released by nonfat cells." (PMID 20508843, 2010). "The associations between leptin, interleukin (IL)-6, and hip radiographic osteoarthritis (OA) have not been reported, and their roles in obesity-related hip OA are unclear." (PMID 20482813, 2010). "Additionally, recent evidence also suggests that obesity is characterized by a low-grade chronic inflammatory state, reflected by elevated levels in several serum inflammatory markers, such as interleukin-6 (IL-6) and C-reactive protein (CRP)." (PMID 20525285, 2010). "Moreover, there is a positive correlation between IL-6 levels and circulating CRP, thus increased levels of IL-6 in obesity can directly or indirectly contribute to the risk to develop multiple chronic diseases." (PMID 19545451, 2009). "Multiple studies have shown that plasma levels of the pro-inflammatory cytokine interleukin-6 (IL-6) are elevated in patients with important and prevalent adverse health conditions, including atherosclerosis, diabetes, obesity, obstructive sleep apnea, hypertension, and frailty." (PMID 19436757, 2009). "Obesity is related to a condition of chronic inflammation characterised by abnormal production of inflammatory cytokines with local effects e.g. TNFα or systemic effects e.g. IL-6, that can contribute to the pathogenesis of malignant diseases." (PMID 20030801, 2009). "Previous studies have shown that innate immune dysfunction, associated with absence of interleukin-6 (IL-6), granulocyte-macrophage colony-stimulating factor, IL-1RI, and IL-18, leads to obesity." (PMID 19865485, 2009). "From this work it is clear that IL-6 has diverse actions including modulating endothelial-dependent vasorelaxation, monocyte differentiation, platelet function, procoagulant state, myocardial hypertrophy, and effects on obesity and intermediary metabolism." (PMID 19936194, 2008). "Serum IL-6 levels are positively correlated with extent of obesity based on body mass index." (PMID 19936194, 2008). "Plasma C-reactive protein (CRP), tumor necrosis factor-α (TNF-α), and interleukin-6 (IL-6), markers of inflammation, levels are elevated in subjects with obesity, insulin resistance, essential hypertension, type 2 diabetes, and CHD, suggesting that low-grade systemic inflammation occurs in them." (PMID 18348729, 2008).
Obesity (continued). "Plasma levels of inflammatory markers such as CRP, TNF-α, and IL-6 are elevated in obesity, insulin resistance, essential hypertension, type 2 diabetes, CHD, and metabolic syndrome X, suggesting that all these disorders are associated with low-grade systemic inflammation." (PMID 18078524, 2007). "In our data, IL6 contributed to obesity and less to the lipids factor." (PMID 18154661, 2007). "Plasma levels of C-reactive protein (CRP), tumor necrosis factor-α (TNF-α), and interleukin-6 (IL-6), markers of inflammation are elevated in subjects with obesity, insulin resistance, essential hypertension, type 2 diabetes, and CHD both before and after the onset of these diseases." (PMID 18078524, 2007). "However, several other fat-secreted substances have been suggested to provide links between obesity and breast cancer, such as adiponectin, hepatocyte growth factor and IL-6, perhaps through interfering with insulin resistance and estrogen synthesis." (PMID 17010200, 2006). "IL-6 plasma levels are significantly increased in murine and human insulin resistance, and obesity." (PMID 17140429, 2006). "Overweight and obesity increased adiposity may enhance a proinflammatory microenvironment through increased production of adipokines such as leptin, visfatin, and resistin, which have been linked to elevated CRP, TNF-α, and IL-6 levels." (PMID 41517610, 2026). "However, in obesity and under metabolic stress, mesenteric adipose tissue undergoes immune remodelling marked by macrophage polarization, Th1/Th17 differentiation, and fibroblast reprogramming driven by TNFα, IL-6, and TGF-β1." (PMID 42307033, 2026). "Moreover, IL-6 has context-dependent roles in obesity and diabetes, suggesting that the IL-6/CERS axis may underlie a shared lipotoxic program when IL-6 drives liver dysregulation in these settings." (PMID 41256541, 2025). "Therefore, the upregulation of IL-6 during obesity may represent an adaptive mechanism aimed at enhancing insulin production and ameliorating glucose tolerance to counteract obesity-related insulin resistance." (PMID 40519917, 2025). "Interestingly, acute IL-6 released from contracting muscle exerts anti-inflammatory effects and may counterbalance the chronic IL-6 elevations characteristic of obesity." (PMID 41463063, 2025). "Moreover, obesity promotes the formation of a specific NK cell subpopulation through the IL-6/Stat3 signaling pathway, which expresses IL6Ra and Colony Stimulating Factor 1 Receptor (Csf1r), contributing to the onset of obesity, insulin resistance, and associated inflammation." (PMID 40564033, 2025). "Therefore, chronically elevated IL-6 may be an important contributor to the decline in muscle mass, strength, and function in people with obesity and T2D, potentially contributing to sarcopenic obesity." (PMID 40171198, 2025). "Additionally, the association between diabetes without obesity and serum IL-6 levels was weakened and lost significance after adjusting for age, which is probably due to the relatively younger age of our study population." (PMID 40095937, 2025). "Some research conveyed that obesity could lead to a proinflammatory environment dominated by high levels of C-reactive protein, interleukin-6, and tumor necrosis factor-α, as well as a relative deficiency of protective immune cell types in the endometrium, which may contribute to EC risk." (PMID 40538813, 2025). "The presence of obesity has been shown to be a pathological process that may induce oxidative stress due to the excretion of pro-inflammatory cytokines from adipocytes such as IL-6 and TNF-α." (PMID 40722609, 2025). "Notably, one study demonstrated that weight loss led to reductions in IL-6, IL-1 receptor antagonist, and CRP, suggesting that obesity-related inflammation may be at least partially reversible." (PMID 40722634, 2025).